IL10 (interleukin 10)
Diseases named in the same sentence as IL10 in open-access papers (continued):
Sharing a sentence is not in itself a finding about the gene and the disease.
asthma (continued). "According to our findings in line with a study performed by other investigations, there is a significant difference in the IL-10 expression between the asthma and control groups." (PMID 35774748, 2022). "Herein, we observed that Vit D significantly decreased expression levels of IL‐6 and IL‐17, whereas levels of the asthma‐protective factor IL‐10 were increased." (PMID 35959262, 2022). "The immunosuppressive role of these cells is attested by the transfer of Tregs that can suppress the main features of experimentally induced asthma via secretion of IL-10 and TGF-β." (PMID 36139733, 2022). "Through transcriptional analysis, it was found that the asthma group had upregulated IL-4, IL-5, and IL-10 expression in lung tissue than the normal group, while MS treatment augmented IL-10 and attenuated the elevation of IL-4 and IL-5." (PMID 35812246, 2022). "To conclude, MS protects asthma-induced pulmonary insult through the IL-10, NF-κB, and p38 MAPK pathway by increasing pulmonary Tregs." (PMID 35812246, 2022). "VD supplementation improved the indicators of asthma and COPD, especially in pulmonary function, SGRQ scores, IL-5, IgE, and IL-10 (in serum VD deficiency group)." (PMID 36520525, 2022). "To clarify the antiasthmatic action of MS, we additionally administered anti-IL-10 antibodies to the asthma-MS mice (labeled as the asthma-MS-anti-IL-10 group), with the relevant isotype control as a control (labeled as the asthma-MS-ISO group)." (PMID 35812246, 2022). "IL-10 secretion by macrophages is reduced in patients with asthma, and this is reflected by a reduced concentration of IL-10 in induced sputum." (PMID 35608088, 2022). "Considering the multifaceted role IL-10 plays in infection and in allergy, a greater understanding of IL-10 during asthma exacerbations is needed." (PMID 35273509, 2022). "Compared with children with normal weight and asthma, leptin and IL-10 were significantly higher in all the obese children, indirectly excluding a role of these cytokines, in particular leptin, for the asthma–obesity phenotype." (PMID 36291398, 2022). "IL-10 has a protective effect in acute inflammatory diseases such as asthma and acute respiratory distress syndrome, but the role of IL-10 in pulmonary fibrosis is unclear." (PMID 36564791, 2022). "Herein, the asthma mice presented drastic reduction of IL-10 secretion accompanied of lower expression of Foxp3 in lung." (PMID 36685604, 2022). "On the contrary, the Imuno TF restored levels of IL-12 (5D), IFN-ɣ (5E), and IL-10 (5F) in lung of asthma mice." (PMID 36685604, 2022). "Non‐T2 cytokines, such as IL‐2, IL‐10, and IFN‐γ, have been implicated in the pathogenesis of asthma, particularly in patients with severe disease." (PMID 35344278, 2022). "Th2 cytokines IL-4, IL-5, and IL-13 were correlated with more severe virus-induced asthma symptoms; whereas IFN-γ (Th1 cytokines) and IL-10 were associated with minor symptoms and conditions (i.e., lower viral load)." (PMID 36362795, 2022). "The vitro model of asthma treated with miRNA-221-5p mimic resulted in the reduction of IL-6, IL-17, IL-21 and IL-22 levels, and induction of IL-10, IL-35 and TGF-β levels." (PMID 34863307, 2021). "This is because it can decrease oxidative stress, serum levels of immunoglobulin E (IgE), IL4, transforming growth factor (TGF-β), and increase interferon-gamma (IFN-γ) and IL-10 in the OVA-induced asthma model." (PMID 33959015, 2021). "In a similar manner, delivery of the dectin-1/TLR2 agonist curdlan, a bacterial cell wall exopolysaccharide, to asthmatic mice induces differentiation of IL-10-expressing, Maf+Foxp3− Treg (i.e., Tr1 cells), and thereby reverses the animal’s asthma phenotype." (PMID 33777019, 2021). "IL-10 especially plays an important inhibitory role—via the inhibition of many effector cells and disease processes—in the pathogenesis of asthma." (PMID 34071080, 2021).
asthma (continued). "The possible mechanism is the increase in Treg cells that produce IL-10 in the lung; in this sense, this therapy can be used as an immunotherapeutic strategy in the treatment of asthma." (PMID 35185864, 2021). "In same vein, other S. mansoni recombinant antigens as Sm22.6, Sm14, P24, and PIII antigen increase IL-10 secretion in cell cultures from subjects with asthma." (PMID 34413850, 2021). "Human umbilical cord blood (hUCB)-MSCs increased the IL-10 production of Tregs in a mouse asthma model." (PMID 34635172, 2021). "IL-10 mRNA levels in serum correlated with AIT efficacy in house dust mite (HDM)-induced asthma in humans." (PMID 34804031, 2021). "The increase of IL-4 and suppression of IL-10 is a valuable tool to show the promotion of asthma in rats sensitized to OVA." (PMID 33794910, 2021). "Specifically, LV-mediated over-expression of IL-10 converted bone marrow-derived DCs into tolDCs that prevented allergic dermatitis in vivo and induced Ag-specific tolerance in an experimental asthma model." (PMID 34445143, 2021). "Our results share several similarities with previous findings that in asthma conditions, secretion of IL-10 was suppressed, which, in turn, induces the production of many pro-inflammatory cytokines." (PMID 33794910, 2021). "For A. lumbricoides, total protein extracts reduce IL-5 and eosinophilia and induce IL-10 to protect mice against experimental asthma." (PMID 34413850, 2021). "One study where exosomes secreted by BM-MSCs were isolated and cultured with PBMCs from patients with asthma demonstrated Tregs modulation in IL-10 and TGF-β1 increase." (PMID 33959015, 2021). "Vitamin D is able to suppress the production of proinflammatory cytokines interleukin-17 (IL-17), IL-13 and promote anti-inflammatory IL-10 and Th2 cell activation, hence preventing the onset of asthma development." (PMID 33919626, 2021). "Patients with neutrophilic asthma and low FEV1 had the fewest IL10+ macrophages of all asthma subgroups, which was significantly different from patients with paucigranulocytic asthma and patients with neutrophilic asthma and normal FEV1." (PMID 35387061, 2021). "Th2 cells protect against parasites but also promote the development of IgE-mediated atopic diseases (asthma), producing cytokines such as IL-4, IL-5 IL-6, IL-9, IL-10, and IL-13." (PMID 34071190, 2021). "Other studies carried out in animal models of asthma also report that this cytokine (IL-10) is able to inhibit airway inflammation and hyperreactivity." (PMID 35185864, 2021). "Genetic variants drive the onset and development of asthma, including cytotoxic T-lymphocyte-associated protein 4 (CTLA4) and interleukin-10 (IL-10) which are involved in immune system regulation and inflammation." (PMID 34525985, 2021). "Our previous study showed an anti-inflammatory effect of the PBM in an acute experimental model of asthma, and we see that this mechanism is partly dependent on IL-10." (PMID 35185864, 2021). "The cytokine IL-10 secreted by M2 macrophages can effectively reduce airway inflammation, promote lung injury repair, and attenuate airway remodeling after asthma." (PMID 33761997, 2021). "Intravenous transplantation of human placental MSCs elevated Tregs and serum IL-10 in the peripheral blood of rats with asthma." (PMID 34635172, 2021). "Nonetheless, the immunosuppressive role of these cells has been confirmed, since transfer of Tregs can suppress the main features of asthma in mice, through secretion of IL-10 and TGF-β." (PMID 34924814, 2021). "Complementing IL-10 expression in CD40-/- DC10 by IL-10 mRNA transfection fully restored the cells’ abilities to suppress the asthma phenotype." (PMID 33793599, 2021). "As shown by the analysis results of the PPI network topology, 13 key targets were screened, and most were inflammatory cytokines, it is worth to note that IL-6, TNF-α, and IL-10 play an important role in the development of asthma." (PMID 34880921, 2021).
asthma (continued). "Both are proinflammatory cytokines that amplify and orchestrate the inflammatory response in asthma and determine its severity; IL-10, a cytokine derived from Th2 cells and 8-Isoprostane (ISO8) a biomarker of oxidative stress were also increased." (PMID 34442368, 2021). "Despite their rather modest basal expression of IL-10, treatment with IL-10-differentiated DCreg (DC10) can reverse the asthma phenotype in mouse models, while human DC10 similarly induce allergen- tolerance among CD4+ T cells of allergic asthma donors." (PMID 33793599, 2021). "In conclusion, the present study suggests that the observed differences in the frequencies of allergen-responsive Foxp3 or IL-10 CD4 T cells are associated with the distinct susceptibility of A/J, BALB/c, and C57BL/6 mice to experimental asthma." (PMID 34924814, 2021). "Prenatal paternal smoking led to epigenetic modifications in certain genes as such as LIM Domain Only 2 (LMO2) and interleukin-10 (IL-10) via cytosine-phosphate-guanine (CpG) methylation, and these modifications are correlated to childhood asthma development." (PMID 32867076, 2020). "IL-10 has wide immunosuppressive and anti-inflammatory properties suitable to attenuate asthma pathology." (PMID 33267824, 2020). "Compared with control and sham acupuncture groups, electroacupuncture upregulates IFN-γ and downregulates IL-4 and IL-10 in bronchoalveolar lavage and pulmonary tissue in asthma rodent model." (PMID 33144870, 2020). "A significant reduction in anti-inflammatory IL-10 levels in patients with asthma was identified when compared to control subjects, and IL-10 secretion was markedly lower in children with atopic dermatitis." (PMID 33490002, 2020). "Studies about the immune-regulatory activity of GMP on other allergic conditions show an increased expression of IL-10 in affected tissue by allergic inflammation, such as lung in asthma and skin in atopic dermatitis." (PMID 32992996, 2020). "An experimental study showed that F. prausnitzii induces human colonic DCs to prime CD4+ and CD39+ expression secreting IL-10 and IL-27, which are known as molecules that play a key role in Foxp3+-Treg generation and regulate asthma." (PMID 33339172, 2020). "Patients with asthma had a relatively reduced ability to produce IL-10 by BALF and mononuclear cells." (PMID 33265990, 2020). "Our results indicated that increased IL-10 responses are derived from PBMCs, indicating that in asthma pathogenesis, systemic immune responses can alter disease severity and clinical features." (PMID 32054098, 2020). "Surprisingly, in our study asthma patients were characterized by IL-10 elevation as compared to controls." (PMID 32685129, 2020). "Th9 cells secrete IL-9, IL-10, and other cytokines, which play essential roles in human asthma pathogenesis." (PMID 32258172, 2020). "The precise role of IL-10 is unclear in asthma pathogenesis, particularly, in steroid-resistant asthmatics, and appears to be pleiotropic." (PMID 32054098, 2020). "The amelioration of OVA-induced asthma by PAS-1 was mediated by IL-10/TGF-β–producing Treg cells (CD4+CD25+) and IFN-γ–producing CD8+ T cells." (PMID 33013887, 2020). "The use of Schistosoma parasite increases the level of IL-10 and decreases the expression of Th2 cytokines and inhibits the progression of asthma." (PMID 32489374, 2020). "It is well recognized that asthma is an immune response driven by Th2 and Th17 cells with cytokines such as IL-4, IL-5, IL-9, IL-10, IL-13, and IL-7 playing important roles." (PMID 33123005, 2020). "Our IL-10 production results stand in contrast to human studies, which showed increased IgE-mediated IL-10 production only in humans with atopic disease (mixed populations of patients had asthma, allergic rhinitis and/or atopic dermatitis)." (PMID 32442209, 2020). "Accordingly, patients with asthma exhibit a higher IL-10 serum level than that of healthy individuals." (PMID 32054098, 2020).
asthma (continued). "The Th2-type cytokines, IL-4, 5, and 13, which are associated with the promotion of IgE and eosinophilic responses mostly in atopy and asthma, and IL-10, characterized by anti-inflammatory response, were explored in ACO." (PMID 32448302, 2020). "The cytokine activin-A induces the generation of IL-10-producing Treg cells (act-A-iTreg cells) that upon therapeutic administration confer significant protection against asthma manifestations." (PMID 33114551, 2020). "For example, the G-protein-coupled estrogen receptor agonist has been found to suppress airway inflammation through IL-10 in a mouse model of asthma." (PMID 32900903, 2020). "Asthma individuals were characterized by increased serum levels of IL-6, IL-10, alanine aminotransferase activity, as well as elevated monocyte, eosinophil, lymphocyte, and total white blood cell (WBC) counts as compared to controls." (PMID 32685129, 2020). "The anti-inflammatory cytokine, IL-10 was least expressed in asthma; the levels in ACO cases were significantly less when compared with COPD and controls." (PMID 32448302, 2020). "This study shows that allergen-derived peptide immunotherapy abrogates asthma-related features in mice and humanized mice by reducing Th2 and Th17 cells polarization via IL-10-secreting DC." (PMID 33312170, 2020). "There was an increased plasma expression of IL-10 and IL-6 in asthma and of c-x-c motif chemokine ligand 2 (CXCL2) and adrenomedullin (ADM) in pulmonary TB." (PMID 33023021, 2020). "OfHz stimulation induced IL-12b, IL-10 expression by immature DC and potentiated LPS-induced expression and production of IL-10 and IL-12β by human DCs in the BA asthma group." (PMID 31750318, 2019). "Upon treatment with corticosteroids and following Allergen Immunotherapy (AIT) the concentrations of the Treg cells and the expression of FoxP3 and IL-10 can be restored and clinical improvement of asthma achieved." (PMID 30967873, 2019). "Helminthic infections activate regulatory T cells and induce the production of IL-10, thereby playing a protective role against asthma and allergies." (PMID 31886302, 2019). "Horses with mild equine asthma have a lower concentration of IL-10 in BAL fluid than healthy controls which concurs with human asthmatics." (PMID 31694631, 2019). "Interleukin 10 and 13 are classified as Th-2 related cytokines, participating in asthma and COPD pathogenesis." (PMID 31363402, 2019). "IL-10 is a regulatory cytokine that is proposed for the treatment of asthma due to its anti-inflammatory properties." (PMID 32641957, 2019). "Studies in utero have shown that maternal famine was associated with higher methylation of IL10, LEP, ABCA1, GNASAS, and MEG3 genes, compared to the same-sex unexposed siblings, potentially increasing risk of asthma later in life." (PMID 32047643, 2019). "What This Study Adds to the Field: Prenatal tobacco smoke (PTS) can program epigenetic modifications in certain genes, such as LMO2 and IL-10, and that these modifications are correlated to childhood asthma development." (PMID 31214241, 2019). "We set out to dissect the mechanism for induction of IL-10 versus IL-17 in T cells, which are critical targets in inflammatory tissues such as the airways in asthma." (PMID 30598515, 2019). "The importance of glucocorticoid-induced IL-10 is highlighted by studies in patients with severe steroid-resistant (SR) asthma, who represent a profound clinical challenge for disease management." (PMID 30598515, 2019). "The production of Th1-promoting cytokine IL-12β and anti-inflammatory cytokine IL-10 by asthma DCs upon OfHz stimulation can suggest a role for Hz released during infection with Opisthorchis felineus in the Th1/Th2 balance regulation." (PMID 31750318, 2019). "In conclusion, our data demonstrate that OfHz induces expression of Th1 cytokines in immature mouse DC and that OfHz potentiates LPS-induced expression and production of IL-10 and IL-12β by DC in asthma patients." (PMID 31750318, 2019).
asthma (continued). "While interleukin 13 is considered as inflammatory promoting, Interleukin 10 has an anti-inflammatory effect and has a low level in patient with asthma and COPD." (PMID 31363402, 2019). "To identify TIGIT+ IL-10+ ILC2s in physiological settings, we took advantage of a severe subacute asthma model with IL-10-Venus reporter mice administered a high dose of papain every three days." (PMID 30683858, 2019). "OfHz potentiated the upregulation by LPS of cytokines IL-10 and IL-12β by human DC but only in the asthma group." (PMID 31750318, 2019). "Horses with mild equine asthma have a lower concentration of IL-10 in BAL fluid than healthy controls, which concurs with human asthmatics; the possible inverse association between equine asthma severity and IL-10 concentration warrants further investigation." (PMID 31694631, 2019). "More importantly, 11 mRNAs were overlapped in our sequencing data, MalaCards database and asthma-associated genes, including IL4, IL-10, MMP9, VCAM-1, Il1rl1, Alox5, Il1rn, Ccr3, Cysltr1, Epx, and Ccl24." (PMID 31231429, 2019). "For the role of Tr, they can also inhibit ILC2s in mouse asthma models via the production of IL-10 and TGF-β." (PMID 31284537, 2019). "Testing and analysis for total IgE, aeroallergen-specific IgE antibodies, serum cytokines IL-4, IL-13, IL-10, and IFN-γ levels, and total peripheral eosinophilic index were used as immunological biomarkers known to be associated with asthma." (PMID 31336954, 2019). "In a small number of adult patients with allergy-induced asthma, MSCs significantly reduced the interferon-γ level and increased the IL-10 level." (PMID 31673233, 2019). "It has been shown that miR-106a-5p targets interleukin-10 (IL-10), an anti-inflammatory cytokine that is defective in many inflammatory diseases including asthma and allergic lung inflammation." (PMID 29739446, 2018). "In this study, we compared the mRNA expression of IL-10 and IL-17A in three distinct groups of healthy control, mild and severe asthma to investigate any relationship between these interleukins with the severity of asthma." (PMID 30915130, 2018). "The serum levels of IL-10 in allergic rhinitis, asthma and complication groups were 9.9, 10.0 and 12.7 times that of the control group (6.15±2.98) ng/L), respectively (Table-I)." (PMID 30344593, 2018). "In this study, we evaluated the expression alteration of Interleukin-10 (IL-10) and Interleukin-17A (IL-17A) in some categories of asthma patients with different level of severity versus healthy controls." (PMID 30915130, 2018). "Our findings showed a significant decreased level of IL-10 in patients with severe persistent asthma compared to those with mild asthma and controls." (PMID 30915130, 2018). "Obtained data revealed that deregulation IL-10 and IL-17A have potential to play crucial role in pathogenesis and prognosis of asthma." (PMID 30915130, 2018). "We predicted percent methylation for each participant at the time of repeat measure using data from 188 subjects (or 179 for IL10) and average normalized methylation to covariates asthma, season, and 90-day average of exposure to a single pollutant." (PMID 29317916, 2018). "Serum IL-4, IL-5, IL-10, adhesion molecules and sE-selectin are all involved in the pathogenesis of allergic rhinitis and asthma, which can be used to evaluate the degrees of respiratory allergic diseases." (PMID 30344593, 2018). "We sought to identify CpG sites in the Foxp3 and IL10 genes that have higher DMRs in children with asthma exposed to AAPs." (PMID 29317916, 2018). "We know that DC10 secretion of IL-10 is a critical element in their abilities to induce tolerance in asthma, such that we were initially surprised that DC10 inhibition of the B cell response was contact-dependent." (PMID 29293622, 2018). "Noteworthy, the down-regulation of IL-17A is more distinctive in all asthma samples in comparison with IL-10 expression level." (PMID 30915130, 2018).